IL13 (interleukin 13)
Diseases named in the same sentence as IL13 in open-access papers (continued):
Sharing a sentence is not in itself a finding about the gene and the disease.
viral infection (continued). "For example, increased tissue pathology during viral infections has been observed, facilitated by promoting a Th2 response, including IL-13 production." (PMID 33562141, 2021). "We were also able to confirm the strong up and downregulation of ACE2 protein levels by virus infection and IL-13, respectively." (PMID 33046696, 2020). "IL-13 and virus infection mediated effects on ACE2 expression were also observed at the protein level in the airway epithelium." (PMID 33046696, 2020). "With the demonstration that expression of human DC-SIGN, murine SIGNR3 and MGL was increased in IL-4/IL-13-stimulated macrophages, we assessed the effect of these receptors on virus infection using carbohydrate-based competitors." (PMID 31825972, 2019). "We postulated that one possible explanation for the limited enhancement by IL-4/IL-13 of virus infection in pmacs is that other receptors utilized by EBOV are also available and utilized in pmacs." (PMID 31825972, 2019). "In total, these data provide strong evidence that SIGNR3 upregulation is a key component of the IL-4/IL-13-mediated increase in virus infection in murine macrophages." (PMID 31825972, 2019). "While the impact of IL-4/IL-13 upregulation of mannose-binding CLRs such as SIGNR3 on virus infection of pmacs is statistically significant, it is a modest effect." (PMID 31825972, 2019). "Regarding a potential effect of blocking IL-13 on viral infections, available evidence from clinical studies with IL-13 blocking antibodies has so far failed to provide any data suggesting clinically relevant impact." (PMID 30759882, 2019). "First, we utilized the cell culture model combining rhinovirus infection and IL-13 treatment, and found that viral infection in both cell types increased the expression of IP-10, although the increase was only significant in the ALI culture." (PMID 29721720, 2018). "In the submerged culture of IL-13 treatment and viral infection, eotaxin 3 responses in both nasal and bronchial epithelial cells followed the same pattern for the ALI culture." (PMID 29721720, 2018). "Third, eotaxin 3 production following IL-13 treatment in both cell types is similar in the absence or presence of viral infection." (PMID 29721720, 2018). "Here L. paracasei–fed mice showed an expansion of TH2 cells after viral infection, which suggest that IL-13 and IL-5 produced by T cells have beneficial effects for the tissue homeostasis." (PMID 28931041, 2017). "First, IL-13−/− and STAT-6−/− mice were far more susceptible to WT or mutant virus infection than IL-4−/− mice." (PMID 25751266, 2015). "Cytokines and chemokines that showed limited response in mice with any viral infection included Eotaxin, GM-CSF, IL-1α, M-CSF, IL-2, IL-3, IL-4, IL-5, IL-7, IL-9, IL-12p40, IL-13, IL-15, IL-17, MIP2, LIX, MIP1β, RANTES, IL-12p70, and VEGF (data not shown)." (PMID 23441208, 2013). "Although IL-4 and IL-13 are predominantly produced by Th2 cells, epithelial cells may also release these cytokines in response to dsRNA or viral infection." (PMID 41576028, 2026). "In the microenvironment of small airway epithelial cells, particularly during viral infections, the presence of IL-4 or IL-13 may enhance the expression of TSLP and IL-8." (PMID 41576028, 2026). "Within the microenvironment of small airway epithelial cells, particularly during viral infections, the presence of IL-4 or IL-13 may augment the expression of TSLP and IL-8." (PMID 41576028, 2026). "However, as noted, there are several additional models of COPD, including those involving enhanced MMP or IL-13 expression, repetitive viral infections, chemical models with vascular endothelial growth factor (VEGF) inhibitors, and NO2 exposure models." (PMID 39512624, 2024). "In this study, we defined the role of PRRSV-induced m6A level in regulating the host inflammatory factor and demonstrated that cellular m6A machinery could increase IL-13 expression induced by viral infection." (PMID 38508309, 2024).
viral infection (continued). "Specifically, ILC2-derived IL-13 drives airway hyperreactivity during multiple viral infections." (PMID 36602520, 2023). "IL-33, an upstream regulator of IL-13 in vivo, can be induced during viral infection." (PMID 38124753, 2023). "We explore the role of IL-13 in maintaining homeostasis at the lung mucosae and propose that its dysregulation during viral infection may propagate the hallmarks of severe disease – further exploration may provide a platform for invaluable therapeutics." (PMID 34027204, 2021). "Moreover, at the later stages of viral infection, Th2 cells can also contribute to the IL-13 environment, impacting the resulting viral load and adaptive immune outcomes." (PMID 34027204, 2021). "In addition, viral infections act in concert with IL-13 to induce the release of chemokines crucial to eosinophilic inflammation, including CCL26 and CCL5, from bronchial epithelial cells." (PMID 32120846, 2020). "IL-33, which is released primarily from the epithelial cells in the lung in response to danger signals (e.g., allergens, viral infection), induces the release of type 2 cytokines, including IL-13, from several innate immune cells in the lung that then promote lung inflammation." (PMID 31118931, 2019). "Also, this study does not address the mechanisms by which nasal and bronchial epithelial cells have similar responses to viral infection and IL-13 treatment." (PMID 29721720, 2018). "Finally, it has been demonstrated that in allergic patients, molecules of the allergic cascade (IL-4, IL-13, IgE receptor) are directly triggered and up-regulated by viral infections of the lower airways." (PMID 31826034, 2018). "Early viral infections of the lower airways lead to a further intensification of the allergic immune reaction and in particular to an expression of the IgE receptor, which further heats up the Th2 cascade (“Il-4/IL-13 storm”)." (PMID 31826034, 2018). "In the second, the IL-4Rα−/− and IL-13−/−/IL-4Rα−/− mice exhibited increased susceptibility to WT virus infection but the absence of vIFN-γbp during infection mitigated the increased susceptibility." (PMID 25751266, 2015). "Furthermore, CGRP may dampen Th2 cell development, which is consistent with recent findings that CGRP–RAMP3 signaling attenuated IL-13 production during viral infection." (PMID 41472747, 2025). "Furthermore, Jartti and collaborators (2014) demonstrated that the presence of viral infection on tonsils or nasopharyngeal mucosa induced an “unexpected” strong correlation between IL-13 and the cluster of antiviral cytokines, which included all types of interferons." (PMID 35686128, 2022). "The observation that STAT6/STING contribute to type I IFN production and survival during primary virus infection suggests that STING and STAT6 may be involved in the control of IL-13 and type I IFN production and susceptibility to post-IAV infection superinfection." (PMID 27143388, 2016). "Viral infection or stimulation with dsRNA can upregulate TSLP expression, an effect that is further amplified in the presence of IL-4 or IL-13." (PMID 41576028, 2026). "ST3GAL2 resists viral infection by downregulating pro-inflammatory cytokines (IL-6, IL-18, IL-1β, IFN-β, TNF-α) and upregulating anti-inflammatory cytokines (IL-4, IL-10, IL-13)." (PMID 40755778, 2025). "During viral infections, STAT1 signaling regulates the balance of ILC subsets, promoting antiviral IFN-γ+ ILC1s while suppressing potentially immunopathologic IL-5+ and IL-13+ ILC2s and IL-17A+ ILC3s." (PMID 40872304, 2025). "Taken together, our results revealed a novel mechanism of inflammatory reaction to viral infection via m6A modification, in which PRRSV nsp9 decreased FTO-bound increasing m6A-modified motifs of IL-13 secretion." (PMID 38508309, 2024). "The immune response to viral infection included an increase in IFN-γ and IL-17 and a decrease in IL-4 and IL-13." (PMID 36768715, 2023).
viral infection (continued). "Type 2 immune-biased hosts, such as asthmatics, in some instances have better outcomes in response to primary viral infections such as SARS-CoV-2 or influenza, perhaps due to IL-13 remodeling of the lung." (PMID 37600776, 2023). "Thus, low IFN and IL‐13 expressions could promote persistence of viral infections." (PMID 34435757, 2021). "Specifically, in the context of viral vector-based vaccination whilst IL-13/STAT6 signalling has been shown to dampen effective antiviral immunity, however in acute and primary viral infections, it has shown to improve antiviral immunity." (PMID 31974500, 2020). "Two murine DC-SIGN-like family members, SIGNR3 and SIGNR5, were upregulated by IL-4/IL-13 in murine macrophages, but only SIGNR3 enhanced virus infection in a mannan-inhibited manner, suggesting that murine SIGNR3 plays a similar role to human DC-SIGN." (PMID 31825972, 2019). "Enhanced IL-4/IL-13-mediated infection was blocked by mannan, indicating that mannose-binding CLRs, such as DC-SIGN, are responsible for the increased virus infection." (PMID 31825972, 2019). "For FVC, statistically significant interactions between viral infection and inflammation were seen for CXCL10 mRNA, TLR3 mRNA, IL-4, IL-13, CCL5, CCL20 and CCL24." (PMID 30463560, 2018). "The production of MIP-1 is caused by various proinflammatory factors and cytokines, such as viral infection, Gram positive bacteria, TNF-a, IFN-γ, IFN7, IL-1 α/β, IL-13 and many others." (PMID 26620310, 2015). "Our data indicate OPN-deficiency led to enhanced mucus secretion and reduced viral loads in the lung; this resembles the phenomena observed when IL-13 and MUC5AC are overexpressed in mice and the animals are protected from viral infection." (PMID 24558422, 2014). "With the hope of understanding how interleukin (IL)-4 and IL-13 modulated quality of anti-viral CD8+ T cells, we evaluated the expression of receptors for these cytokines following a range of viral infections (e.g. pox viruses and influenza virus)." (PMID 23383283, 2013). "Interferon (IFNβ and IFNλ1) gene expression was increased after viral infection in healthy as well as asthmatic BECs, and treatment with IL-4 or IL-13 did not modulate this antiviral response." (PMID 40370530, 2025). "By studying a series of viruses, we have recently shown that ILC2s produce significant IL-13 following viral infection/vaccination 24 h post-encounter, where the level of ILC2-derived IL-13 is dependent on the virus (e.g., fowlpox <influenza <rhinovirus <Vaccinia virus)." (PMID 34027204, 2021). "The leading contribution of MCs in response to viral infection might be in the context of the producing panel of mediators (amines, tryptase, chymase) and cytokines/chemokines (TNF-α, IL-4, IL-5, IL-6, IL-13, and IL-17)." (PMID 32185237, 2020). "Mannan, but not GalNac, specifically reduced virus infection of IL-4/IL-13 polarized murine pmacs and human MDMs, indicating that mannose binding receptors were responsible for mediating virus uptake." (PMID 31825972, 2019). "In our longitudinal study, we found that, in the absence of viral infection, CXCL10, IL-4, IL-13, CCL4, CCL5, CCL20 and CCL24 were each negatively associated with FVC." (PMID 30463560, 2018). "Furthermore, IL-33 links viral infection, macrophages, and ILC2-dependent production of IL-13 to AHR and induces ILC2- and IL-13-dependent DC trafficking to the lymph nodes, promoting Th2 adaptive immunity." (PMID 29915592, 2018). "For example, in the absence of viral infection, CXCL10 mRNA, MDA5 mRNA, CXCL10, IL-4, IL-13, CCL4, CCL5, CCL20 and CCL24 were negatively associated with FVC." (PMID 30463560, 2018). "Blocking IL-13 failed to reduce viral infection of AECs, ASM mass, or cytoplasmic HMGB1 levels in AECs." (PMID 28099113, 2017). "This could be due to the extra IL-4/IL-13 we supplied to the cell culture, which may not be present in an in vivo setting during viral infection." (PMID 36129169, 2022).
viral infection (continued). "We found that IL-4/IL-13 enhanced virus infection of pmacs by about 3 to 3.5-fold, regardless of whether PS liposomes were present suggesting these receptors do not mediate the IL-4/IL-13-enhanced infection." (PMID 31825972, 2019). "However, as TIM-4 expression was not enhanced by IL-4/IL-13 treatment, this receptor cannot be responsible for the increase in virus infection mediated by IL-4/IL-13." (PMID 31825972, 2019). "We speculate that viral load is mainly controlled by the amount of goblet cells induced by IL-13, while IP-10 production may come from non-goblet cells (e.g., ciliated cells) that are more prone to viral infection with subsequent IP-10 production." (PMID 29721720, 2018). "The mechanism underlying this prevention appears not to be due to a simple reduction in IL‐13, but may involve multiple innate cells early in the viral infection." (PMID 28474501, 2017). "IL-13-induced eotaxin-3 production was similar in both types of cells under either submerged or ALI culture, which was not affected by viral infection." (PMID 29721720, 2018). "Meanwhile, the levels of IL-5 and IL-13, which are Th2 cytokines, were significantly higher in the BALF of OVA mice than those of PBS mice before infection (Day 0) although they declined after infection (Day 3) regardless of virus infection." (PMID 28245238, 2017).
breast carcinoma (69 papers, 2007 to 2026). "Type II IL4R is expressed on epithelial cancer cells, including breast cancer, responds to stimulation by either IL4 or IL13, and its elevated expression is associated with breast cancer metastasis." (PMID 40663259, 2025). "A study of 398 breast cancer patients prior to surgery showed that the rs1295686*A of IL13 was associated with a symptom cluster of pain, fatigue, sleep disturbance, and depression." (PMID 37510364, 2023). "By using differential analysis method, found that two haplotypes (ACA and CCA) of three variants in gene IL-13 were significantly associated with risk for breast cancer." (PMID 38292437, 2023). "Pain following breast cancer treatment is significantly associated with the inflammatory cytokine gene IL13 and lymphatic gene VEGFC." (PMID 35037883, 2022). "We found one SNP in IL-13 associated with breast cancer among women of East Asian descent that remained statistically significant after multiple testing correction, and this was replicated in the SBCGS." (PMID 30601841, 2019). "Following FDR correction, the SNP rs1800925 (IL-13) was associated with breast cancer risk (OR = 2.08 (95% CI: 1.32–3.28) p = 0.000779; after correction padj = 0.0350)." (PMID 30601841, 2019). "One study among 398 breast cancer patients prior to surgery found that the A allele of IL-13 (rs1295686) was associated with a symptom cluster of pain, fatigue, sleep disturbance, and depression." (PMID 27555379, 2017). "Similar to the pattern in ER+ disease, IL13 was marginally associated with poor clinical outcome in ER- breast cancer." (PMID 21050467, 2010). "We observed similar patterns of association in Set2, and in particular while IL12, IL2 and IFNG were associated with good prognosis in ER- breast cancer, IL13 correlated with poor outcome." (PMID 21050467, 2010). "Rs1800925 in IL-13 was significantly associated with breast cancer in one of two data sets tested, as well as in an overall meta-analysis of the SBCGS data (4305 cases and 4194 controls; OR 1.12, (95% CI: 1.03–1.21) p = 0.011), with the same direction of association as in the Canadian data." (PMID 30601841, 2019). "Because we found that targeting IL13Rα2 enhances STAT6 phosphorylation by IL-13, we hypothesized that this induction may be implicated in modulating the tumorigenic and metastatic properties of breast cancer cells." (PMID 26208975, 2015). "Furthermore, IL-13 is overexpressed in various solid tumors and is associated with poor prognosis in conditions such as glioblastoma, colorectal cancer, adrenocortical carcinoma, pancreatic cancer, and breast cancer." (PMID 40236667, 2024). "While the control group generally exhibited low baseline levels of circulating cytokines, breast cancer patients demonstrated significantly elevated concentrations of multiple cytokines, including IL-1β, IL-6, IL-8, IL-12 (p40), IL-13, G-CSF, TNF-α, and MCP-1." (PMID 40612845, 2025). "IL-5 and IL-13 have been reported as elevated in some breast cancers, with a potential role for IL-5 in enhancing the response to an immune checkpoint blockade." (PMID 38397942, 2024). "In breast cancer, IL-33 secreted by cancer-associated fibroblasts enhances ILC2 and Th2 type responses, induces the TCR-independent secretion of IL-13, and recruits immunosuppressive granulocytes." (PMID 40236667, 2024). "M2 macrophage infiltration assays indicated that PAZ@Fe-MOF treatment significantly decreased the infiltration of IL-4/IL-13-stimulated THP-1 cells (M2-like macrophages) into breast cancer tissues." (PMID 39033109, 2024). "MDSC activation in breast cancer has been shown to be induced by the IL-13 secreted from group 2 innate lymphoid cells (ILC2s)." (PMID 35805039, 2022). "Studies using a 4T1 breast cancer mouse model have shown that ILC2-derived IL-13 promotes 4T1 lung metastasis via the activation of the IL-13Rα1 expressed in MDSCs." (PMID 35805039, 2022).